NEAT1 (nuclear paraspeckle assembly transcript 1)
Diseases named in the same sentence as NEAT1 in open-access papers (continued):
Sharing a sentence is not in itself a finding about the gene and the disease.
lung adenocarcinoma (16 papers, 2018 to 2026). A carcinoma that arises from the lung and is characterized by the presence of malignant glandular epithelial cells. "MALAT1 (metastasis associated lung adenocarcinoma) and NEAT1 (nuclear enriched abundant transcript 1) are highly abundant types of nuclear lncRNA, that localizes to the nuclear speckles and paraspeckles respectively." (PMID 37153158, 2023). "The data reveal that NEAT1 expression is dysregulated in lung adenocarcinoma; its high expression is associated with shorter overall survival of patients with lung adenocarcinoma." (PMID 29788922, 2018). "Herein, we investigated whether abnormal NEAT1 overexpression is associated with NF-κB activation in lung adenocarcinoma." (PMID 29788922, 2018). "A recent study reported a NEAT1-miR-101-3p/335-5p/374a-3p/628-5p-TRIM6 network in lung adenocarcinoma, whose hyper-activation results in upregulated TRIM6 level and poorer prognosis." (PMID 38813007, 2023). "Galectin-3 and TLR4 expression are abnormally up-regulated in lung adenocarcinoma tissues, and positively correlated with NEAT1 expression." (PMID 29788922, 2018). "The data indicate that Galectin-3 induces TLR4/NF-κB signaling activation, followed by NEAT1 expression upregulation, and ultimately promotes lung adenocarcinoma cell proliferation and migration." (PMID 29788922, 2018). "Herein, we validated the increased NEAT1 expression in lung adenocarcinoma specimens, as well as the correlation between higher NEAT1 expression and shorter overall survival in patients." (PMID 29788922, 2018). "Inhibiting Galectin-3-induced TLR4 signaling activation, thus to reduce p65-activated NEAT1 expression might be a promising strategy of suppressing lung adenocarcinoma cell proliferation and migration." (PMID 29788922, 2018). "In lung adenocarcinoma, LPS stimulation also caused a remarkable increase in TLR4, MyD88 and p-p65 protein expression, as well as NEAT1 mRNA expression, which could be partially reversed by CLI-095, an inhibitor of TLR4 signaling." (PMID 29788922, 2018). "We confirmed that Galectin-3 as a ligand of TLR4 induced TLR4 signaling activation in lung adenocarcinoma cells, thereby activating downstream p65 nucleus translocation, promoting NEAT1 expression, and finally affecting lung adenocarcinoma cell proliferation and migration." (PMID 29788922, 2018). "Whether NF-κB can be aberrantly activated by upstream regulators, thus activating NEAT1 expression in lung adenocarcinoma still remains unclear." (PMID 29788922, 2018). "Investigating the upstream regulators and mechanisms of NEAT1 expression disorders may provide a novel perspective to modulate lung adenocarcinoma cell hyperproliferation and migration." (PMID 29788922, 2018). "Here, we explored the upstream regulatory factors and mechanisms of NEAT1 abnormal overexpression in lung adenocarcinoma, and further suggest a regulatory path formed by Galectin-3, TLR4, NF-κB and NEAT1 that may contribute to the hyperproliferation and migration of lung adenocarcinoma cells." (PMID 29788922, 2018). "Herein, we also observed that Galectin-3 overexpression remarkably induced TLR4 protein expression, as well as lung adenocarcinoma cell proliferation and migration; next, we further investigated whether Galectin-3 exerts its function through downstream NF-κB and NEAT1." (PMID 29788922, 2018).
lung adenocarcinoma (continued). "NEAT1 overexpression also promotes lung adenocarcinoma cell proliferation and migration; thereby, investigating the mechanism of abnormal NEAT1 overexpression and rectifying the dysregulation of NEAT1 may represent a promising strategy for lung adenocarcinoma treatment." (PMID 29788922, 2018). "The data indicate that Galectin-3 and TLR4 expression are abnormally up-regulated in lung adenocarcinoma tissues; Galectin-3 affects lung adenocarcinoma cell proliferation and migration through activating TLR4/NF-κB pathway and NEAT1 expression." (PMID 29788922, 2018). "Galectin-3 reportedly serves as a ligand of TLR4 and promotes TLR4, MyD88 and p-p65 expression; we investigated whether Galectin-3 could modulate lung adenocarcinoma cell proliferation and migration through TLR4/NF-κB/NEAT1." (PMID 29788922, 2018).
neuroblastoma (16 papers, 2015 to 2025). Neuroblastoma (NB) is the most common solid, extracranial childhood tumor. "The application of ASOs that target the NEAT1 isoform switch region sterically block NEAT1_1 polyadenylation and trigger the loss of NEAT1_1 transcripts concomitant with high levels of the NEAT1_2 isoform, and have a tumour-suppressive effect in neuroblastoma cells." (PMID 35457249, 2022). "NEAT1_2 upregulation leads to the inhibition of neuroblastoma cell proliferation, migration, and invasion." (PMID 38891878, 2024). "MiR-107 abundance is diminished in Aβ-treated SH-SY5Y neuroblastoma cells, and NEAT1 overexpression reverses Aβ-induced injury." (PMID 34421536, 2021). "Consistent with data from neuroblastoma cells, paraspeckle numbers and NEAT1 positive area were increased ~ 2-fold in mutant FUS fibroblasts." (PMID 30642400, 2019). "Neuroblastoma cells were transfected with siRNAs targeting TDP-43 or another Microprocessor component Drosha alone or in combination with NEAT1 siRNA." (PMID 29859124, 2018). "Our data clearly prove that an increase of NEAT1 level by SFN causes no harm in the in vitro neuroblastoma cell PD model." (PMID 40234480, 2025). "However, neither enoxacin nor other agents (such as histone deacetylase inhibitors) that induced NEAT1_2 and de novo paraspeckles in neuroblastoma cells were able to evoke paraspeckle assembly in human embryonic cell-derived motor neurons." (PMID 36385948, 2022). "Moreover, miR-519a-3p was discovered to hinder MPP+-evoked apoptosis and inflammation in neuroblastoma cells via the NEAT1/miR-519a-3p/SP1 axis." (PMID 35350655, 2022). "Furthermore, when we measured NEAT1 levels in neuroblastoma cells expressing untagged CREST or GFP vector, we observed a significant decrease in the transcript abundance in CREST-expressing cells." (PMID 25888396, 2015).
thyroid cancer (16 papers, 2018 to 2024). "NEAT1, an up-regulated lncRNA in thyroid cancer, has been reported to induce tumor-associated macrophages via sponging miR-214 and inducing the β-catenin/Wnt signaling pathway." (PMID 33158279, 2020). "MiR-592 suppresses the malignant phenotypes of thyroid cancer through the regulation of lncRNA NEAT1 and downregulation of NOVA1." (PMID 36467881, 2022). "In this section, we summarize and discuss the role of the NEAT1/miRNA/target axis in thyroid cancer, a type of endocrine system tumor." (PMID 34512157, 2021). "β-catenin is a direct target of miR-214 and participates in the malignant behavior of NEAT1-induced thyroid cancer." (PMID 32596158, 2020). "This further highlights the therapeutic potential of NEAT1 as a potential target for thyroid cancer therapy." (PMID 33158279, 2020). "These highlight the importance of targeted inhibition of NEAT1 to overcome the chemotherapy and radioactivity iodine-resistance of thyroid cancer patients." (PMID 33158279, 2020). "NEAT1 is overexpressed in thyroid cancer tissues and cells compared to levels in normal thyroid tissues and cells." (PMID 32596158, 2020). "Knockdown of NEAT1 inhibited migration, invasion, and cell survival of thyroid cancer, accompanied by decreased expression of β-catenin (a direct target of miRNA-214)." (PMID 31777603, 2019). "Studies have found that NEAT1 and Arg-1 were highly expressed in thyroid cancer patients, and miR-214 was expressed at a basal level." (PMID 31777603, 2019). "For example, lncRNA NEAT1 promotes malignant progression of thyroid cancer via the regulation of miRNA-21421." (PMID 29515098, 2018). "Notably, NEAT1 has two transcripts, and some miRNAs can only interact with NEAT1-2, such as miR-491 and miR-106b-5p, which promote the metastasis and growth of thyroid cancer." (PMID 36011001, 2022). "MiR-592 decreases thyroid cancer progression by modulating lncRNA NEAT1/NOVA1 signaling." (PMID 34290668, 2021). "In addition, overexpression of NEAT1 is correlated with thyroid cancer progression by sponging miR214 and downregulation of NEAT1 is associated to suppression of PTC progression via the miR1295p/KLK7 axis." (PMID 32760219, 2020). "LncRNA NEAT1 has been shown to have therapeutic implications in different thyroid cancer types." (PMID 33158279, 2020). "Sedaghati summarized the dysregulated and functional LncRNAs in thyroid cancer, including 28 upregulated LncRNAs, such as ANRIL, BANCR, H19, HOTAIR, MALAT1, and NEAT1, and 22 downregulated LncRNAs, including GAS5, NAMA, PTCSC2, and PTCSC3." (PMID 37874339, 2024). "The studies found that Neat1 can inhibit the expression level of PTEN in laryngeal cancer and thyroid carcinoma to promote malignant biological behavior of tumors." (PMID 36335386, 2022).
esophageal squamous cell carcinoma (15 papers, 2017 to 2024). Esophageal squamous cell carcinoma (ESCC) is a type of esophageal carcinoma (EC) that can affect any part of the esophagus, but is usually located in the upper or middle third. "Others have shown activation of NEAT1 expression also promoted proliferation, migration, and invasion of Esophageal squamous cell carcinoma." (PMID 36923505, 2023). "LncRNA NEAT1 sponges miR-129 to regulate the progression of esophageal squamous cell carcinoma via increasing CTBP2 expression." (PMID 32351327, 2020). "Long noncoding RNA nuclear paraspeckle assembly transcript 1 (NEAT1) was reported to be aberrantly upregulated and promote esophageal squamous cell carcinoma (ESCC) cell progression." (PMID 29147064, 2017). "Furthermore, NEAT1 sponged miR-129 in esophageal squamous cell carcinoma and hepatoblastoma." (PMID 31868202, 2020). "The aim of this study is to verify the function and potential mechanisms of lncRNA NEAT1 in progression and angiogenesis of esophageal squamous cell carcinoma (ESCC)." (PMID 33680941, 2020). "LncRNA nuclear paraspeckle assembly transcript 1 (NEAT1) sponged to miR-129, leading to the depression of CTBP2 and regulated the esophageal squamous cell carcinoma (ESCC) cell viability and invasion." (PMID 34068010, 2021).
papillary thyroid cancer (14 papers, 2018 to 2023). "lncRNA NEAT1 acts as an oncogene in papillary thyroid cancer by regulating the miR‐129‐5p/KLK7 axis." (PMID 35242185, 2022). "NEAT1 contributed to radioactive iodine resistance via PI3K/Akt signaling pathway in papillary thyroid carcinoma." (PMID 32268876, 2020). "For instance, NEAT1 was considered to be a competing endogenous RNA to modulate the expression of ATAD2 by suppressing miR-106b-5p in papillary thyroid cancer." (PMID 30053878, 2018). "Long non-coding RNA (lncRNA) nuclear-enriched abundant transcript 1 (NEAT1) exerts a pro-oncogenic role in several cancers, whereas its underlying regulatory mechanism in papillary thyroid carcinoma (PTC) progression remains unknown." (PMID 35635748, 2022). "In addition, NEAT1 was found to promote papillary thyroid cancer through regulating ATAD2 expression by sponging miR-106b-5p31." (PMID 30154460, 2018). "NEAT1 competitive binds to miR-129-5p and leads to inhibited papillary thyroid cancer progression." (PMID 30518750, 2018). "For instance, NEAT1 could inhibit papillary thyroid cancer progression by upregulating miR-129-5p." (PMID 33574830, 2020). "However, the function of NEAT1 in papillary thyroid cancer (PTC) is not well understood." (PMID 29515109, 2018). "In papillary thyroid cancer (PTC), the molecular mechanism by which NEAT1 affects invasion and metastasis remains elusive." (PMID 33738254, 2021).
HIV-1 infection (13 papers, 2015 to 2025). The type species of lentivirus and the etiologic agent of acquired immunodeficiency syndrome (AIDS). "We conclude that ZBTB11-AS1 and NEAT1 exhibit changes in their expression and subcellular localization during different HIV-1 infection stages in the C20 human microglial cell line." (PMID 40429887, 2025). "NEAT1 is an lncRNA that has been widely studied in various pathologies, including HIV-1 infection in other target cells." (PMID 40429887, 2025). "In this study, we analyzed the relationship between HIV-1 infection and two lncRNAs, NEAT1 and ZBTB11-AS1, on different days post-infection." (PMID 40429887, 2025). "It was observed that HIV-1 infection downregulates the expression of NEAT1 lncRNA leading to the reduction of the number of host-protective paraspeckle bodies, hence increased HIV-1 expression within CD4+ T lymphocytes." (PMID 34737736, 2021). "HIV-1 infection downregulates the expression of NEAT1 which would otherwise restrict HIV-1 replication through sequestration of unspliced viral RNA into paraspeckles." (PMID 34737736, 2021). "The expression of NEAT1 was changed by HIV-1 infection and knockdown of NEAT1 enhanced virus production through increased nuclear to cytoplasmic export of Rev-dependent INS-containing HIV-1 mRNAs." (PMID 28603696, 2017). "The expression of NEAT1 is significantly reduced in HIV-1-infected patients treated with highly active antiretroviral therapy, suggesting that NEAT1 may be involved in the immune response to HIV-1 infection." (PMID 40362651, 2025). "Furthermore, some authors suggested that the presence of NEAT1 in plasma is a potential biomarker of HIV-1 infection." (PMID 34737736, 2021). "HIV-1 infection can up-regulate the expression of lncRNA NEAT1." (PMID 32674073, 2020). "Additionally, NEAT1 is changed by HIV-1 infection, and knockdown of NEAT1 can enhance virus production by increasing nucleus-to-cytoplasm export of HIV-1 mRNA." (PMID 29599646, 2018). "We also noted that the expression levels of NEAT1 and ZBTB11-AS1 varied during these different stages of HIV-1 infection in microglia, as did their subcellular localization." (PMID 40429887, 2025). "NEAT1 is a well-known lncRNA and is identified as an antiviral in an HIV-1 infection context; its knockdown promotes viral production in CD4+ T cells because NEAT1 sequesters gRNA in nuclear paraspeckles." (PMID 40429887, 2025). "Previously known lncRNAs 7SK RNA, NEAT1, NRON repress HIV-1 infection, and lncRNAs uc002yug. activates HIV-1 replication and reactivates HIV-1 from latency." (PMID 30788509, 2019). "A group identified six lncRNAs that were dysregulated by HIV-1 infection in both Jurkat and MT4 cells, one of which is NEAT1 (Nuclear Paraspeckle Assembly Transcripts 1)." (PMID 29426337, 2018). "The observed changes, akin to those in NEAT1, suggest that ZBTB11-AS1 could play an antiviral role in HIV-1 infection within microglia, but this should be further evaluated in future studies." (PMID 40429887, 2025). "In this study, we aimed to evaluate two lncRNAs that had not been detected in microglia during HIV-1 infection in previous studies: NEAT1 and ZBTB11-AS1." (PMID 40429887, 2025). "Interestingly, transcript levels of both MALAT1 and NEAT1 have been shown to be upregulated in PBMCs of HIV-1-infected patients, and, notably, expression of NEAT1 correlated with CD4+ T cell counts, indicating potential function of these lncRNA during HIV-1 infection." (PMID 31336952, 2019).
pulmonary fibrosis (13 papers, 2022 to 2025). Chronic progressive interstitial lung disorder characterized by the replacement of the lung tissue by connective tissue, leading to progressive dyspnea, respiratory failure, or right heart failure. "NEAT1 has been shown to be associated with the development of various tumors and plays a role in pulmonary fibrosis." (PMID 41268559, 2025). "According to the literature, GOLM1 can upregulate NEAT1 to promote pulmonary fibrosis, which is a major characteristic of BPD, before the implementation of antenatal steroids and surfactant therapy." (PMID 40098026, 2025). "When lncRNA NEAT1 is knocked out, it can inhibit hypoxia-induced apoptosis of alveolar epithelial cells and reduce the level of pulmonary fibrosis index protein." (PMID 40110044, 2025). "Upregulated NEAT1 expression was involved in the development of fibrosis in various organs, including pulmonary fibrosis." (PMID 39524435, 2024).
renal fibrosis (13 papers, 2020 to 2025). A final common manifestation of a wide variety of chronic kidney diseases characterized by glomerulosclerosis and tubulointerstitial fibrosis. "The first is the nuclear enriched abundant transcript 1 (NEAT1) that regulated Akt/mTOR signaling, which is a pathway associated with EMT in renal fibrosis progression." (PMID 41233312, 2025). "LncRNA NEAT1 accelerates renal fibrosis progression via targeting miR-31 and modulating RhoA/ROCK signal pathway." (PMID 39133718, 2024). "Depletion of NEAT1 suppressed the expression of the EMT-related markers, such as vimentin and a-SMA, and the renal fibrosis-associated markers, including TGF-β1 and CTGF." (PMID 36313695, 2022). "Recent evidence demonstrates that lncRNAs also mediate renal fibrosis in DN, such as the lncRNA NEAT1 and lncRNA ASncmtRNA-2 which induce kidney fibrosis in DN, and 1700020I14Rik and lncRNAGm4419 which attenuate kidney fibrosis in DN." (PMID 33324218, 2020). "Neat1 was also induced during the progression of renal fibrosis." (PMID 34697716, 2022). "Under hyperglycemia, the expression of NEAT1 was up-regulated in DN and led to renal tubular epithelial-mesenchymal transition (EMT) and renal fibrosis." (PMID 36154667, 2022). "Silencing NEAT1 in HK2 cells resulted in inhibition of the EMT-related markers alpha smooth muscle actin (α-SMA) and vimentin (VIM) and the renal fibrosis-related markers transforming growth factor-β1 (TGF-β1) and connective tissue growth factor (CTGF)." (PMID 32054986, 2020). "Furthermore, lncRNA NEAT1 sponged miR-129 to modulate the EMT process and inflammation response of renal fibrosis by regulating collagen I expression." (PMID 37872392, 2023).